SNHG12 (small nucleolar RNA host gene 12)
Diseases named in the same sentence as SNHG12 in open-access papers (continued):
Sharing a sentence is not in itself a finding about the gene and the disease.
cancer (continued). "Additionally, upregulated SNHG12 expression play important roles in the cellular process of tumorigenesis, including cancer cell proliferation, migration, invasion, apoptosis, epithelial-mesenchymal transition(EMT) and chemoresistance." (PMID 33124951, 2020). "The aggregated data suggested that high expression level of SNHG12 was significantly correlated to poor OS (HR = 1.97, 95%CI: 1.56–2.48, p < 0.001), indicating that lower SNHG12 expression in cancer patients may suggest a better survival outcome." (PMID 33124951, 2020). "Our work will be the first study using system review methodology to quantitatively evaluate SNHG12 significance on survival and clinicopathological outcomes in human pan-cancers, which would further address the feasibility of SNHG12 as a prognostic candidate in cancers." (PMID 33124951, 2020). "Moreover, SNHG12 was also reported to be involved in the tumorigenesis of other cancers by interacting with miR-129-5p/WWP1, miR-195/CCNE1, miR-125-5p/MDM4, miR-326/E2F1, and miR-15a-5p/SALL4 axes." (PMID 33294456, 2020). "Moreover, these differential mechanisms also made SNHG12 a potential therapeutic target for respective treatment of corresponding cancer types as well." (PMID 33294456, 2020). "Therefore, there is still much uncertainty for the prognostic value of SNHG12 in cancers, and a systematic analysis is still needed to clarify this issue, which, however, has not been explored so far as we know." (PMID 33294456, 2020). "As hypothesized, KLF5 expression was positively correlated with that of SNHG12 in both cancer and normal tissues." (PMID 32943987, 2020). "Several investigations have revealed that SNHG12 could function as competing endogenous RNA (ceRNA) by binding to miRNA, thereby regulating target genes in multiple human cancers." (PMID 33124951, 2020). "Therefore, we conducted a meta-analysis complemented with bioinformatics analysis to elucidate the clinical significance of SNHG12 in cancer patients." (PMID 33294456, 2020). "However, majority of studies evaluating the prognostic potential of SNHG12 in cancer survival outcomes have been limited by their small sample size and discrete outcomes." (PMID 33124951, 2020). "Additionally, SNHG12 was also reported to facilitate cancer growth by activating various signaling pathways, promoting epithelial-mesenchymal transition (EMT), or serving as competing endogenous RNAs (ceRNAs)." (PMID 33294456, 2020). "The present findings indicated that SNHG12 might act as a novel biomarker for diagnosis or prognosis in human cancers." (PMID 33294456, 2020). "Moreover, upregulated SNHG12 expression holds the strong significance on clinicopathological outcomes of cancer patients." (PMID 33124951, 2020). "Targets/pathways of SNHG12 in different tissues/cell lines in various cancers." (PMID 31620362, 2019). "Thus, in this review we have discussed the importance of small nucleolar RNA host gene 12 (SNHG12), a lncRNA, as a potential biomarker for a variety of cancers." (PMID 31620362, 2019). "In another study, low plasma levels of SNHG12 were reported in 10 pre-operative GC patients compared to their post-operative samples and 10 healthy controls, which is in contrast to its expression in cancer tissue samples." (PMID 31620362, 2019). "SNHG12 played important roles in cancer cell proliferation and migration." (PMID 28941134, 2018). "The apoptotic rate of A549/DDP, A549/PTX and PC9/AB2 cells was indeed elevated by treatment with either anti-cancer drugs (cisplatin, paclitaxel and gefitinib) or (si-SNHG12-1 or si-SNHG12-2), while simultaneous SNHG12 downregulation and drug treatment led to significantly higher apoptotic cells." (PMID 29137407, 2017). "Notably, MEG3, MIAT, Malat1, SNHG20, SNHG12, Ftx, Pvt1, Mir9-3hg expression in cancer immune cells was associated with an immunosuppressive phenotype, while H19, SNHG6, Trp53cor1, MiR17hg and MiR142hg were linked to a pro-inflammatory phenotype in cancer." (PMID 40527978, 2025).
cancer (continued). "Furthermore, SNHG12 may serve as a promotor in multiple cancer-related pathways, such as Slug/zinc finger E-box-binding homeobox 2 (ZEB2) pathway, Notch2/Notch pathway, phosphatidylinositol 3-kinase (PI3K)/AKT pathway, and Wnt/β‐catenin signaling pathway." (PMID 33124951, 2020). "Besides, SNHG12 could be involved into cancer progression by interacting with various kinds of signaling pathways." (PMID 33124951, 2020). "Moreover, as distant metastasis is an important reason for failure of cancer therapy, SNHG12 might also serve as a potential therapeutic target for preventing metastasis in diverse cancer types." (PMID 33294456, 2020). "Moreover, knockdown of SNHG12 in GC cell lines significantly up-regulated the levels of both the miRNAs showing a negative correlation between the two and reversing the effect of SNHG12 in cancer progression." (PMID 31620362, 2019). "Moreover, SNHG12 played important roles in cancer cell proliferation and migration." (PMID 28225893, 2017). "Several differentially expressed lncRNA in fibroid from postmenopausal women have been shown to have oncogenic roles in different types of cancer including HOTTIP, SNHG12, CASC15, ZEB2-AS1." (PMID 40725045, 2025). "Among the 22 SNHG families, SNHG5, SNHG7, SNHG12, and SNHG16 are all known to promote cancer progression." (PMID 37189636, 2023). "Among the 12 m6ARLncRNAs, LINC01138, SNHG12, ITGA9‐AS1, and TSPOAP1‐AS1 were involved in malignant phenotypes of cancers." (PMID 35726651, 2023). "In estrogen receptor-positive cancer with mass lesion type, CCL3L1 (21-fold), SNHG12 (11-fold), and MIR206 (sevenfold) were upregulated, and MIR597 (265-fold), MIR126 (12-fold), and SOX17 (fivefold) were downregulated." (PMID 37391754, 2023). "Meanwhile, SNHG12 can promote the malignancy of clear cell RCC by competitively binding with miR-30a-3p and consequently releasing the expression of its downstream cancer-related genes." (PMID 35597996, 2022). "Several lncRNAs, such as SNHG12, PVT1, and LINC00672, were shown to function crucially in carcinomas." (PMID 35341001, 2022). "We found that over-expression of SNHG12 and SNHG20 in LIHC had significant alteration across cancer stages, representing their roles in cancer progression and invasion." (PMID 35140741, 2021). "These lncRNAs can be either upregulated (e.g., ANRIL, SNHG12, NEAT1 in some cancers, PVT1) or downregulated (e.g., GAS5, NEAT1 in APL) in order to promote cell proliferation and migration, and prevent apoptosis of cancerous cells." (PMID 30654440, 2019). "Another interesting lncRNA present in this group is the Small Nucleolar RNA Host Gene 12 (SNHG12), that plays an oncogenic role in various cancers." (PMID 30211115, 2018). "The carcinogenesis function of SNHG family in cancers has been widely reported, and the participation of SNHG1 and SNHG7 in ESCC has been researched, so we focused on SNHG12 in our research." (PMID 32239639, 2020). "In addition, we also found that the L-FFL motif comprised of E2F1, miR-195 and SNHG12, and the L-FFL motif comprised of E2F1, miR-106b and KB-1732A1.1, were dysregulated in three types of cancers." (PMID 27322142, 2016). "Of them, SNHG12 has been reported to be up-regulated in human endometrial cancer, bladder cancer, nasopharyngeal cancer, colorectal cancer, lung adenocarcinoma, breast cancer, liver cancer, and clear cell RCC, and plays an important role in the proliferation and migration of cancer cells." (PMID 35597996, 2022). "Thus, it is possible that SNHG12 may also influence the unfolded protein response (UPR), which is stabilized in a large variety of cancers in a MAPK-dependent manner." (PMID 31620362, 2019). "In ER-positive cancers, CCL3L1, SNHG12, and MIR206 were upregulated 21-fold, 11-fold, and sevenfold, respectively, in mass–type cancers, compared to non-mass enhancement–type cancers." (PMID 37391754, 2023).
cerebral artery (2 papers, 2021 to 2022). "By overexpressing Snhg12 after middle cerebral artery occlusion in mice, Zhang and colleagues were able to show decreased infarct volumes." (PMID 34793334, 2022).
metabolic disorders (1 paper, 2025). "Overall, these findings suggest that SNHG12 alleviates metabolic disorders and promotes ovarian follicle development in PCOS mice." (PMID 40486908, 2025).
SNHG12 also shares sentences with these, for which no sentence is quoted: aortic atherosclerosis (1 paper); Atherosclerotic lesion (1); blood cancer (1); bone metastasis (1); brain infarcts (1); cancers of the reproductive system (1); digestive system cancer (1); infection (1); latent infection (1); MELAS (1); metastatic tumours (1); oral squamous cell carcinoma (1); osteoarthritis (1); osteoma (1); polycystic ovary syndrome (1); rectal adenocarcinoma (1); renal clear cell sarcoma (1); Stroke (1).